CX3CL1 (C-X3-C motif chemokine ligand 1)
Diseases named in the same sentence as CX3CL1 in open-access papers (continued):
Sharing a sentence is not in itself a finding about the gene and the disease.
A further 103 diseases each share a sentence with CX3CL1 in 1 paper.